H3P6 (H3 histone pseudogene 6)
Synonyms: p13; formerly H3F3AP4
Gene: Processed pseudogene on chromosome 2 (174,719,908 to 174,720,318, forward strand). Ensembl gene ENSG00000235655.
Diseases named in the same sentence as H3P6 in open-access papers:
H3P6 is named in the same sentence as 1 disease in open-access papers, as found by Europe PMC text mining. Sharing a sentence is not in itself a finding about the gene and the disease.
H3P6 shares sentences with these, for which no sentence is quoted: cancer (1 paper).